CDCA8 (cell division cycle associated 8)
Description:
Component of the chromosomal passenger complex (CPC), a complex that acts as a key regulator of mitosis. The CPC complex has essential functions at the centromere in ensuring correct chromosome alignment and segregation and is required for chromatin-induced microtubule stabilization and spindle assembly. Major effector of the TTK kinase in the control of attachment-error-correction and chromosome alignment.
Synonyms: FLJ12042; MESRGP; BOR; DasraB; BOREALIN
Tractability: Small molecule: a structure with a bound ligand is known. PROTAC: UniProt records ubiquitination sites on it; ubiquitination databases record sites on it; its protein half-life has been measured.
Gene: Protein-coding gene on chromosome 1 (37,692,481 to 37,709,719, forward strand). Ensembl gene ENSG00000134690.
Subcellular location: Nucleus, nucleolus; Cytoplasm; Cytoplasm, cytoskeleton, spindle; Chromosome, centromere
Subcellular location (Human Protein Atlas): Nucleoli; Cytokinetic bridge; Nucleoplasm
Pathways (Reactome):
Cell Cycle: Amplification of signal from unattached kinetochores via a MAD2 inhibitory signal; EML4 and NUDC in mitotic spindle formation; Mitotic Prometaphase; Resolution of Sister Chromatid Cohesion; Separation of Sister Chromatids
Metabolism of proteins: SUMOylation of DNA replication proteins
Signal Transduction: RHO GTPases Activate Formins
Gene Ontology:
Molecular function: protein binding
Biological process: chromosome organization; mitotic metaphase chromosome alignment; mitotic cell cycle; mitotic cytokinesis; mitotic sister chromatid segregation; mitotic spindle assembly; mitotic spindle midzone assembly; positive regulation of attachment of mitotic spindle microtubules to kinetochore; positive regulation of mitotic cell cycle spindle assembly checkpoint; positive regulation of mitotic cytokinesis; positive regulation of mitotic sister chromatid separation
Cellular component: chromosome passenger complex; chromosome, centromeric region; cytoplasm; microtubule cytoskeleton; midbody; nucleolus; protein-containing complex; cytosol; nucleoplasm; spindle midzone; chromocenter; spindle
Genetic constraint (gnomAD): Loss-of-function variants: 16 observed, 25.74 expected, observed/expected ratio (o/e) 0.62, 90% interval 0.42 to 0.94. The upper end of that interval is the gene's LOEUF score, 0.94, which puts it in group 4 of 6, group 1 being the genes least tolerant of losing a copy. Missense variants: 201 observed, 284.51 expected, observed/expected ratio (o/e) 0.71, 90% interval 0.63 to 0.79. Synonymous variants: 98 observed, 108.09 expected, observed/expected ratio (o/e) 0.91, 90% interval 0.77 to 1.07.
Homologues: Orthologues: chimpanzee CDCA8 (99% identical), macaque CDCA8 (97% identical), pig CDCA8 (89% identical), rabbit CDCA8 (88% identical), dog CDCA8 (87% identical), guinea pig CDCA8 (85% identical), rat Cdca8 (80% identical), mouse Cdca8 (79% identical), tropical clawed frog cdca8 (42% identical), zebrafish cdca8 (32% identical).
Diseases named in the same sentence as CDCA8 in open-access papers:
CDCA8 is named in the same sentence as 61 diseases in open-access papers, as found by Europe PMC text mining. Sharing a sentence is not in itself a finding about the gene and the disease. The quoted sentences say what the papers report.
breast carcinoma (27 papers, 2016 to 2025). "Overexpression of CDCA8 in breast cancer was reported to be associated with triple-negative phenotype and a shorter overall survival." (PMID 35627287, 2022). "Cell division cycle‐associated 8 (CDCA8), a regulator of mitosis, is overexpressed in bladder cancer, breast cancer, liver cancer, and other tumors and is involved in their growth and development." (PMID 34523732, 2021). "One study also reported that CDCA8 was significantly linked to poor prognosis in patients with cutaneous melanoma, breast cancer, colorectal cancers and lung cancer." (PMID 32716971, 2020). "CDCA8 is an essential regulator of mitosis, and its overexpression is significantly associated with bladder cancer, cutaneous melanoma, and the progression and prognosis of breast cancer." (PMID 33564675, 2021). "CDCA8 is related to the distant metastasis risk of breast cancer." (PMID 32104702, 2020). "MYBL2 knockout markedly reduced CDCA8 mRNA expression and protein secretion in breast cancer tissues, while MYBL2 overexpression significantly upregulated CDCA8 gene expression and protein level." (PMID 38961953, 2024). "CDCA8, a cytoskeletal protein, plays a role in cytoskeletal assembly and cell movement and has important effects on tumor metastasis and proliferation in breast cancer, bladder cancer and lung cancer." (PMID 38961953, 2024). "Previous investigation had proved that MYBL2 played a role in proliferation, invasion and migration through the regulation of CDCA8 in breast cancer cell." (PMID 38961953, 2024). "Studies revealed that CDCA8 accelerates breast cancer cell cycle progression by suppressing apoptosis, while enhancing tamoxifen resistance and cell proliferation." (PMID 36855818, 2023). "Meanwhile, CDCA8 knockdown also inhibits cell proliferation and promotes cell differentiation in colorectal cancer, lung cancer, breast cancer, cutaneous melanoma, and human embryonic stem cells." (PMID 36158697, 2022). "It has been shown that the CDCA8 gene is highly expressed in breast cancer cells and that CDCA8 gene knockdown can inhibit the survival and growth of cancer cells." (PMID 35449575, 2022). "Another CPC component, cell division cycle associated 8 (CDCA8, alias Borealin/DasraB), has been found to be involved in the development of breast cancer, cutaneous melanoma and bladder cancer 18-21." (PMID 35517403, 2022). "Overexpression of CDCA8 in tumour tissues is observed in multiple cancers, including melanoma, bladder cancer, and breast cancer." (PMID 31285741, 2019). "According to the PPI networks, five hub genes (TPX2, KIF2C, CDCA8, BUB1B, and CCNA2) were identified as key genes associated with breast cancer progression." (PMID 31285741, 2019). "Five hub genes, including TPX2, KIF2C, CDCA8, BUB1B, and CCNA2, were validated to be notably associated with the shorter DMFS of breast cancer in the patient cohort based on KM Plotter." (PMID 31285741, 2019). "Overall, we identified five genes (TPX2, KIF2C, CDCA8, BUB1B, and CCNA2) associated with distant metastasis, indicating these genes as potential biomarkers for assessing the risk of breast cancer recurrence and distant metastasis." (PMID 31285741, 2019). "The survival analysis of breast cancer patients with high CDCA8 expression levels showed a poor prognosis value, with an HR of 1.98." (PMID 29467944, 2018). "One meta-analysis using public microarray data and immunohistochemistry revealed that the overexpression of CDCA8 in breast cancer, especially TNBC, reduced patient survival." (PMID 29467944, 2018). "Our data showed that CDCA8 had a high expression level in the male breast carcinoma, invasive lobular breast carcinoma, invasive ductal breast carcinoma, and invasive breast carcinoma subtypes." (PMID 29467944, 2018).
breast carcinoma (continued). "In a similar expression pattern to CDCA3 and CDCA5, a high expression level of CDCA8 also correlated with a bad prognosis for breast cancer patients with a shorter RFS." (PMID 29467944, 2018). "We also found that AURKB, BIRC5, CDCA8, and FOXM1 are all part of the meta-PCNA proliferation gene signature, and high levels of expression of genes in this signature are associated with poor prognosis in breast cancer." (PMID 39335162, 2024). "CDCA8 is, therefore, a key mediator of estrogen-stimulated breast cancer cell growth and survival." (PMID 35449575, 2022). "High expression of CDCA3 and CDCA8 had been found in breast cancer, resulting in a poor prognosis." (PMID 34053447, 2021). "CDCA8 induces tamoxifen resistance in breast cancer cells and promotes their proliferation." (PMID 34741389, 2021). "Cell division cycle associated 8 (CDCA8) over-expression is related to mitosis and tumor growth and may act as a prognosis biomarker in bladder cancer, cutaneous melanoma, breast cancer and osteosarcoma." (PMID 32266115, 2020). "Altogether, these findings suggested CDCA3, CDCA5, and CDCA8 could have a high potency as targeted breast cancer therapies." (PMID 29467944, 2018). "Similarly, previous studies had stated that ASPM, CDC20, BUB1B, and CDCA8 expression could be potential poor survival prognostic biomarkers in lung adenocarcinoma, prostate/breast cancer, glioblastoma, respectively." (PMID 36186000, 2022). "Moreover, overexpressed CDCA8 is critical for the growth of embryonic stem cells and breast cancer." (PMID 34741389, 2021). "Five hub genes (TPX2, KIF2C, CDCA8, BUB1B, and CCNA2) associated with the risk of distant metastasis were extracted for further research, which might be used as biomarkers to predict distant metastasis of breast cancer." (PMID 31285741, 2019). "CACNA1B, CDCA8, and RGMA were identified as prognostic factors and a promising therapeutical target in breast cancer." (PMID 40665355, 2025). "In breast cancers, we found significant upregulation of KIFC1, AURKB, BIRC5, and CDCA8 in tumor samples of both the GEPIA and UALCAN datasets, compared to normal samples." (PMID 39335162, 2024). "In breast cancer datasets, we found significant upregulation of both centrosome clustering proteins KIFC1, AURKB, BIRC5, and CDCA8 and the oncogenes FOXM1, ATAD2, and E2F1 in tumor samples compared to normal samples." (PMID 39335162, 2024). "CDCA3, CDCA5, and CDCA8 are overexpressed and function as oncogenes in HCC and gastric and breast cancer." (PMID 34660326, 2021). "CDCA8 was often studied in bladder cancer and breast cancer, CDCA8 and FOXM1 appeared to be related in breast cancer." (PMID 31139013, 2019). "By analyzing the various tumor subtypes and cell lines of breast cancer, we found evidence for CDCA3, CDCA5, and CDCA8 involvement in breast cancer, resulting in an overall poor prognosis." (PMID 29467944, 2018). "With the exception of UQCRH and LRP8, the expression levels of genes positively correlated with YBX1, such as CTPS1, FMNL2, CDC20, B3GNT5, MTHFD1L, and CDCA8, were significantly and positively correlated with the expression level of YBX1 in 13 breast cancer cell lines." (PMID 30647855, 2018). "Finally, five hub genes (TPX2, KIF2C, CDCA8, BUB1B, and CCNA2) were identified for further research, which might be used as promising biomarkers to evaluate the distant metastasis of breast cancer." (PMID 31285741, 2019). "In addition, we confirmed that the expression levels of the three genes, ASPM, CDCA8 and KIF2C, were significantly reduced following the knockdown or silencing of FOXM1 based on both microarray data in BT-20 breast cancer cells (GSE2222) and RNA-seq data in MCF-7 breast cancer cells (GSE58626)." (PMID 33667222, 2021). "Interestingly, in another human mammary epithelial cell line (HMEC) (GSE62425), the binding of FOXM1 to CDCA8 was absent, suggesting the emerging binding of FOXM1 to certain genes during the formation of breast cancer." (PMID 33667222, 2021).
lung cancer (23 papers, 2016 to 2025). A malignant neoplasm involving the lung. "Meanwhile, high expression of CDCA8 in gastric cancer, lung cancer and colon cancer were associated with poor prognosis of patients 26-29." (PMID 35517403, 2022). "Human cell division cycle associated 8 (CDCA8) a key regulator of mitosis, has been described as a potential prognostic biomarker for a variety of cancers, such as breast, colon and lung cancers." (PMID 33685433, 2021). "CDCA8, a regulator of cell mitosis, was shown to be associated with lung cancer when it was phosphorylated at four positions, Ser154, Ser219, Ser275, and Thr278, by aura kinase B." (PMID 29467944, 2018). "CDCA8 overexpression was reported in human breast, gastric, and lung cancers, implying that CDCA8 is essential for the growth and development of certain cancers." (PMID 37853361, 2023). "Previous studies have reported CDCA8 overexpression contributes to the proliferation of tumour cells, such as colorectal cancer and lung cancer cells." (PMID 33685433, 2021). "Some studies have suggested that the CDCA8-AURKB pathway is a promising therapeutic target for lung cancer patients via activation of the Wnt/β-catenin signaling pathway." (PMID 32922438, 2020). "Immunohistochemistry shows that overexpression of cell division cycle associated 8 (CDCA8) and AURKB can result in bad outcome of lung cancer patients; thus, suppression of the CDCA8-AURKB pathway is a potential therapeutic strategy for lung cancer." (PMID 27610375, 2016). "Similarly, CDCA8 contributes to epithelial-mesenchymal transition (EMT) in lung cancer, a process essential for metastasis." (PMID 39924497, 2025). "Furthermore, AURKB, CCNB2, CDC20, CDCA5, CDCA8, CENPF, and KNTC1 are were highly expressed in lung cancer tissues and were associated with poor prognosis." (PMID 35598017, 2022). "However, previous studies have shown that CDCA8 can also be expressed in tumor cells, including breast, bladder, and lung cancers." (PMID 36358852, 2022). "Additionally, aurora kinase B-mediated phosphorylation and activation of CDCA8 plays a major role in human lung cancer." (PMID 35354488, 2022). "Several human cancers, including lung cancer, bladder cancer, and hepatocellular carcinoma, have reported that CDCA8 could serve as a poor prognostic marker." (PMID 36358852, 2022). "Furthermore, CDCA8 knockdown also inhibits cell proliferation and promotes cell differentiation in lung cancer, colorectal cancer, and human embryonic stem cells." (PMID 33685433, 2021). "The upregulation of CDCA8 has been reported in diverse types of cancer, including colorectal, breast, gastric, and lung cancer, implying that inhibition of CDCA8 expression could be an effective therapeutic strategy." (PMID 33801424, 2021). "CDCA8, involving in protein metabolism and mitosis, has been demonstrated to participate in malignant progression of tumor cells and lead to poor prognosis in liver, stomach and lung cancer." (PMID 32887635, 2020). "In summary, through WGCNA and differential gene expression analysis, our study generated the significant genes, ASPM, CDCA8, CENP5, CEP55, and PLK1 that may be biomarkers and has potential for treatment in HIV‐infected lung cancer." (PMID 35608130, 2023). "Other genes, including PLK1, CDCA8, ANLN, and RACGAP1, were all discovered to play different roles in proliferation, metastasis, and enhanced chemotherapy sensitivity to doxorubicin in lung cancer." (PMID 35464867, 2022). "Also specific to the epithelial compartment, we observed enrichment for a signature conferring poor outcome in lung cancer, which included general cancer prognostic genes like AURKB, EXO1, MAD2L1, CDCA8, and kinesins like KIF15." (PMID 32883324, 2020). "Among them, five genes (ASPM, CDCA8, CENPF, CEP55, and PLK1) were present in both three hub gene lists (intersection gene, DEGs, and WCGNA module) suggesting that these five genes may become key genes involved in HIV‐infected lung cancer." (PMID 35608130, 2023).
bladder cancer (21 papers, 2017 to 2024). "In the results of multivariate COX regression analysis based on cancer-specific survival, CDCA8 expression was significantly associated with the prognosis of patients with bladder cancer (P = 0.036)." (PMID 32377458, 2020). "The expression of CDCA8 is closely associated with tumor progression, N stage, T stage, and grade of bladder cancer." (PMID 32104702, 2020). "Associations between CDCA8 expression and clinicopathological factors of patients with bladder cancer." (PMID 30142792, 2018). "In this study, we explored the biological functions of cell cycle division-related gene 8 (CDCA8) in bladder cancer (BCa) cells in the hypoxic settings." (PMID 37813876, 2023). "CDCA8 knockdown also suppresses T24 and 5637 cell proliferation, migration, and invasion while accelerating apoptosis of bladder cancer cells." (PMID 36855818, 2023). "Recent studies have shown that CDCA8 is overexpressed in various cancer cells, such as bladder cancer, breast cancer, and cutaneous melanoma." (PMID 36358852, 2022). "The IHC results also showed that CDCA8 expression in bladder cancer was significantly higher than that in normal tissues and was higher in patients with high stage and grade." (PMID 32377458, 2020). "The results of GSE65635 dataset analysis also showed that CDCA8 expression in bladder cancer was significantly higher than that in normal tissues (P < 0.01)." (PMID 32377458, 2020). "To further understand the role of CDCA8 in bladder cancer, we used T24 cells and 5637 cells to carry out the function experiment of CDCA8 in vitro." (PMID 32377458, 2020). "To further explore the effect of CDCA8 expression on the progression of bladder cancer, we obtained the CDCA8 expression value of each sample from the GSE13507 dataset and divided the samples into groups according to the clinical information of GSE13507." (PMID 32377458, 2020). "Compared with normal bladder tissues, CDCA8 expression in bladder cancer tissues in the GSE7476 dataset was significantly higher than that in normal bladder tissues (P < 0.01)." (PMID 32377458, 2020). "This study demonstrated that CDCA8 promotes the of bladder cancer via bioinformatics and in vitro cell experiments." (PMID 32377458, 2020). "We extracted the expression values of CDCA8 from normal tissues and bladder cancer tissues in each dataset." (PMID 32377458, 2020). "Kaplan–Meier and COX regression method were used to analyse the correlation between CDCA8 expression in bladder cancer and prognosis." (PMID 32377458, 2020). "Results showed that CDCA8 was highly expressed in bladder cancer compared with normal tissues, and the high CDCA8 expression was significantly correlated with the poor prognosis of patients." (PMID 32377458, 2020). "This study aimed to reveal the function of CDCA8 in bladder cancer by determining the relationship between CDCA8 expression and proliferation, metastasis and apoptosis of bladder cancer cells." (PMID 32377458, 2020). "In conclusion, our results suggest that CDCA8 is highly expressed in bladder cancer and can promote tumour development." (PMID 32377458, 2020). "We also studied the effect of CDCA8 expression knockdown on cell cycle in T24 and 5637 cell lines, we found that knocking down CDCA8 expression can lead to S and G2/M phase arrest and inhibit the proliferation of bladder cancer cells." (PMID 32377458, 2020). "We also analysed the correlation of CDCA8 expression and prognosis in bladder cancer in the TCGA database." (PMID 32377458, 2020). "Inhibiting CDCA8 expression inhibited the proliferation, migration and invasion of T24 and 5637 cells and induced the apoptosis of bladder cancer cells." (PMID 32377458, 2020). "In order to understand the regulatory mechanism of CDCA8 in bladder cancer, we calculated the CDCA8 co-expressed genes based on the transcriptome data of 414 bladder cancer samples in the TCGA database." (PMID 32377458, 2020).